CD44 (CD44 molecule (IN blood group))
Diseases named in the same sentence as CD44 in open-access papers (continued):
Sharing a sentence is not in itself a finding about the gene and the disease.
breast carcinoma (continued). "Western blotting displayed that E2 could increase ERα expression levels in ZR‐75‐1 and MCF‐7 cells, suggesting a significant positive correlation between ERα and CD44 in ER+ breast cancer cells." (PMID 30179299, 2018). "In breast cancer, a change in CD44 alternative splicing is involved in stemness." (PMID 29356399, 2018). "In addition, they proved that there is a correlation between elevated levels of HA synthesis, CD44 expression and cancer cell migration, consequently highlighting that HA metabolism plays a pivotal role in the aggressive breast cancer phenotype." (PMID 30135409, 2018). "In addition, four cytokeratin genes (KRT8, KRT16, KRT17, and KRT19) and eight tumor-associated genes (TERT, MUC16/M17S2/CA125, CD44, TWIST1, TACSTD1/EpCAM/CD326/ESA/HEA125/GA733, DPP4/CD26, ESR1, and PGR), were upregulated in CRC and breast cancer samples." (PMID 29882767, 2018). "In addition, QKI and RBFOX1 overexpression also significantly increased the CD44-high cell populations in two additional breast cancer cell lines (MCF7 and ZR75-1)." (PMID 30059005, 2018). "CD44+CD24- subpopulation has been regarded as a marker of CSCs in breast cancer cells." (PMID 29298343, 2018). "Indeed, 38 of the 112 (31%) breast cancer cases showed a strong membranous positivity for CD44 in most tumor cells." (PMID 29306324, 2018). "CD44 is also one of the well-known markers of breast cancer-initiating cells (BCIC)." (PMID 29483847, 2018). "In addition, CD44+/CD24−/low CSC subset in breast cancer is resistant to radiation via activation of ATM signaling but does not depend on alteration of nonhomologous end joining (NHEJ) DNA repair activity." (PMID 29681949, 2018). "Interestingly, overexpression of CD44, the receptor of HA in mammary carcinoma or melanoma cells, inhibits tumor growth and metastasis." (PMID 30135409, 2018). "CD44 regulates progression and metastasis of several cancers such as breast cancer, prostate cancer, and melanoma by interacting with extracellular matrix that promotes cell motility and has an affinity for other ligands, including matrix metalloproteinases (MMPs)." (PMID 30157785, 2018). "Among all the common targets of QKI and RBFOX1, we found that CD44 (IC:0.857, p value:<6.59e-07) and FLNB (IC:0.848, p value:<6.59e-07) scored as the top two genes that most strongly associated with the EMT signature in breast cancer cell lines." (PMID 30059005, 2018). "In addition, the HER2-STAT3 network has been shown to contribute to the aggressive phenotype of breast cancer stem cells, and the JAK2/STAT3 signaling pathway is required for the growth of CD44+CD24− stem cell-like breast cancer cells in human tumors." (PMID 29636641, 2018). "Finally, we selected 245 cases CD44+CD24− (breast cancer stem cells phenotype marker) breast cancer patients from TCGA dataset to analyze correlation of EPAS1 with Wnt and Notch pathways related factors, and c-Myc." (PMID 30340507, 2018). "Zerumbone downregulated the basal level of CD44 expression in breast cancer cells." (PMID 29747682, 2018). "Interestingly, in this study, a high expression of CD44 was positively correlated with ERα existed in our established paclitaxel‐resistant ER+ breast cancer cells." (PMID 30179299, 2018). "HMMR, a breast cancer susceptibility gene in BRCA1 mutation carriers, encodes a non-integral hyaluronan receptor that promotes breast cancer migration and invasion in concert with the integral hyaluronan receptor CD44." (PMID 29566768, 2018). "CD44 is used as a CSC marker for breast cancer and EpCAM is used as a CSC marker for HCC." (PMID 29298343, 2018). "Furthermore, we established paclitaxel‐resistant breast cancer cell lines and determined the function of ERα in the enhancement of paclitaxel resistance via the regulation of CD44 transcription." (PMID 30179299, 2018).
breast carcinoma (continued). "Our result indicating that only very few patients showed potential breast cancer stem cell markers, CD44+/CD24- (one out of 99 patients) or ALDH1 (four out of 99 patients) may be in accordance with previous studies of proof of concept on cancer stem cells." (PMID 29416796, 2018). "CD44+CD24low population is considered as stem cells of breast carcinoma." (PMID 29734730, 2018). "However, the regulation of CD44 alternative splicing has not been fully understood in basal‐like breast cancer." (PMID 29356399, 2018). "To further confirm whether IBC reduced the expression of CD44 by regulating the ERα pathway, we carried out the ERα interference experiment in paclitaxel‐resistant breast cancer cells." (PMID 30179299, 2018). "In gastric and breast cancers, CD44 expression is considered as a solid biomarker of CSCs." (PMID 30046596, 2018). "In translational studies, residual tumor specimens collected from women with operable ER+ breast cancer following neoadjuvant letrozole contain a significantly enriched CD44+/CD24low/− subpopulation and upregulation of mesenchymal genes as compared to their pre-treatment tumor." (PMID 29289986, 2018). "Previously, high expression of CD44 correlated with downregulated HER2 in breast cancer cell lines." (PMID 30134903, 2018). "Foxp3 and CD44 protein levels were inversely correlated in several breast cancer cell lines." (PMID 29747682, 2018). "There is a noticeable link between CD44 expression and breast cancer aggressiveness." (PMID 29483847, 2018). "In this study, for the first time, we correlated ERα and CD44 expression, revealing a potential mechanism that ERα could enhance paclitaxel resistance in ER+ breast cancer cells by up‐regulating CD44 expression." (PMID 30179299, 2018). "Our in vitro and in vivo findings highlight the crucial roles of BMP-2, Rb, and CD44 in breast cancer metastasis, which may provide new strategies for determining the prognosis and treatment of advanced breast cancer." (PMID 29339728, 2018). "ESRP1 negatively regulates EMT by preventing CD44 isoforms switch in breast cancer cells." (PMID 29747682, 2018). "Overall, our data demonstrated for the first time that IBC could decrease CD44 expression level via the ERα pathway and make ER+ breast cancer cells sensitive to paclitaxel treatment." (PMID 30179299, 2018). "This study aimed to explore whether IBC influences resistance of breast cancer cells to paclitaxel by regulating CD44/CD24 expression." (PMID 30179299, 2018). "In our study, we proposed the following drug resistance model: during paclitaxel therapy for breast cancer, paclitaxel can active ERα expression and then ERα can transcriptionally regulate the CD44 gene, which is responsible for resistance to chemotherapy agents." (PMID 30179299, 2018). "Besides, SENP2 participates in sphere formation and expression of CD44, a cell surface marker for breast cancer stem cells." (PMID 29955155, 2018). "Interestingly, extracellular HA binding to CD44-RHAMM complexes confers malignant potential in breast cancer." (PMID 29212185, 2017). "Here we demonstrate clear heterotypic interaction between CD74 and CD44, which might act in synergy and hence contribute to breast cancer progression." (PMID 29190904, 2017). "CD44 3′ UTR overexpressed in breast cancer cells could interact with endogenous miRNAs to arrest their mRNA-targeting function." (PMID 29037220, 2017). "In our study, we found that IGF2 could activate Hedgehop signal pathway in the breast cancer cells in the presence of CD44+Fbs." (PMID 28523716, 2017). "As reduced doxo resistance in CD44+/CD24- breast cancer cells is evidenced by suppression of CD44, we analyzed mRNA and protein levels for CD44; the result reveals MCF7/ADR cells with ∼150- and 16-fold higher levels of mRNA and protein, respectively, than in MCF7." (PMID 29050299, 2017).
breast carcinoma (continued). "Moreover, it has been found that only a fraction of CD44+/CD24−/low breast cancer cells were ALDH1 positive, and these cells were more tumorigenic compared to the ALDH1 negative population." (PMID 29062075, 2017). "This study provided results that expression types of DACH1 and CD44 were opposite in breast cancer." (PMID 28659634, 2017). "The CD44+/CD24–/ALDH+ phenotype is thought to increase tumourigenicity of breast cancer cells." (PMID 28707729, 2017). "Breast cancer stem-like cells (BrCSCs) are identified with cell surface phenotypes of either CD44+/CD24− or aldehyde dehydrogenase 1 (ALDH1), and it is now widely accepted that BrCSCs are functionally essential for tumor formation, progression, and therapy resistance in breast cancer patients." (PMID 29262559, 2017). "In addition, epithelial mesenchymal transition (EMT) inducers can induce breast cancer cells to breast CSCs enriched with the CD44+/CD24- configuration." (PMID 29050299, 2017). "CD44 is recognized as a cancer stem cell marker and is enriched in basal-like breast cancers." (PMID 28778177, 2017). "Importantly, we found that IGF2 secretion from CD44+Fbs activates Hedgehog signal pathway to increase breast cancer cell growth and induce drug resistance." (PMID 28523716, 2017). "Moreover, silencing PRDM14 reduced the expression of CD44, which imparts cancer stemness, and STAT3, which is required for growth of CD44+CD24– stem cell-like breast cancer cells." (PMID 28423353, 2017). "CD44 is a cell surface receptor expressed by many cell types, including breast cancer stem cells that interacts with a variety of effectors and initiates many regulatory mechanisms related to adhesion, cell proliferation, migration, invasiveness, and chemo-resistance." (PMID 28052035, 2017). "On the other hand, CD44 has been shown to suppress the growth and metastasis of breast cancer." (PMID 28881705, 2017). "Indeed, scanning electron microscopy showed CD44+CD24-/low breast cancer cells at the tumor invasive protrusions." (PMID 28052035, 2017). "In breast cancer, Mani and colleagues reported that the overexpression of Twist, Snail or FOXC2 not only made the breast cancer cells with more mesenchymal properties, but also with an increased expression of CD44+/CD24-/low breast CSC markers and an increased mammosphere forming efficiency." (PMID 28245823, 2017). "Similarly, the CSC population as defined by the cell surface markers CD44+/CD24- was significantly increased in both breast cancer cell lines by leptin." (PMID 28542577, 2017). "CD44 has been the subject of research interest because of its potential role in breast cancer." (PMID 29190904, 2017). "CPM also significantly reduced levels of CD44+/CD133+ breast cancer stem cells." (PMID 28956452, 2017). "This hypothesis may be associated with the high reproductive skew represented in the MMC model, and some markers (e.g. CD44+/CD24− for breast cancer) to distinguish cancer stem cells have already been developed." (PMID 28989791, 2017). "Notably, it has been demonstrated that CD44+ breast cancer stem cells had a relatively high level of STAT3 activation." (PMID 29036915, 2017). "Notably, rhBMP-2 promoted the formation of tumor spheroids and increased the population of CD44+/CD24− cells in MCF-7 breast cancer cells in this study." (PMID 28725489, 2017). "Both CD44 and hyaluronic acid are expressed in breast cancer cells, thus CD44 could potentially engage to hyaluronic acid present at the counterpart membrane of the contacted cell." (PMID 28894989, 2017).
breast carcinoma (continued). "The migration of CD44-blocked MDA-MB-231 cells to BMCM was only reduced to a level similar to untreated cells exposed to BMCM depleted of OPN, suggesting that CD44 specifically contributes to the effect of bone-derived OPN on breast cancer cell migration (P>0.05)." (PMID 28498874, 2017). "The results indicated that CD44+Fbs could make breast cancer cells more proliferating than CD44−Fbs." (PMID 28523716, 2017). "Our in vitro and in vivo findings highlight the crucial roles of BMP-2, Rb, and CD44 in breast cancer metastasis, which may provide new strategies for the treatment and prognosis of advanced breast cancer." (PMID 28725489, 2017). "Furthermore, STAT3-mediated tamoxifen resistance also has been shown in the CD44+/CD24−/low subpopulation of MCF-7 breast cancer stem cells characterized by their high mammosphere formation capacity." (PMID 29036915, 2017). "In summary, measuring the co-expression levels of CD74 and CD44 could potentially be used as a ‘biomarker signature’ for examining different stages of breast cancer." (PMID 29190904, 2017). "Breast cancer cells undergoing epithelial to mesenchymal transition (EMT) acquire a CD44+/CD24-/ALDH1+ cancer stem cell-like phenotype characterized by an increased capacity for tumor self-renewal, intrinsic drug resistance and high proclivity to develop distant metastases." (PMID 29207686, 2017). "Expression profiling revealed 780 genes for which the expression level was affected by the loss of DIP2C, including the tumour-suppressor encoding CDKN2A gene, the epithelial-mesenchymal transition (EMT) regulator-encoding ZEB1, and CD44 and CD24 that encode breast cancer stem cell markers." (PMID 28716088, 2017). "Furthermore, LDR exposure also reduces sphere formation and inhibits the self-renewal ability of breast cancer cells, resulting in an attenuated CD44+/CD24− population." (PMID 28240233, 2017). "Measuring the co-expression levels of CD74 and CD44 could potentially be used as a ‘biomarker signature’ to monitor different stages of breast cancer." (PMID 29190904, 2017). "Emerging evidence suggests that a small subpopulation of tumor cells, identified by the CD44+/CD24−/low cancer stem cell markers expression in breast cancer tissue, have strong abilities of self-renewal and are responsible for tumor aggressiveness, recurrence, metastasis, and therapeutic resistance." (PMID 28399903, 2017). "Indeed, the examined breast cancer cell lines are characterized by different proportion of CD44 and CD24 expressing cells." (PMID 27845900, 2017). "CD44 plays an important role in metastasis by participating in a variety of signaling networks that promote migration, invasion, growth and survival and our lab has recently showed that breast cancer cells preferentially migrate toward lung-derived OPN in a CD44-dependent manner." (PMID 28498874, 2017). "Furthermore, high CD44 and low CD24 expression, characteristics associated with the breast cancer stem cell phenotype and the EMT state, was revealed in DIP2C KO cells, with potential implications for treatment and metastasis ability." (PMID 28716088, 2017). "HA/CD44 signaling is also involved in the invasive behavior of breast cancer cells." (PMID 29062810, 2017). "In this study, we cocultured CD44+Fbs or CD44−Fbs and breast cancer cells and found that CD44+Fbs could promote breast cancer cell proliferation and suppress cell apoptosis induced by paclitaxel." (PMID 28523716, 2017). "Furthermore, small hairpin RNA-mediated CBX7 knockdown in breast epithelial and breast cancer cells increased the CD44+/CD242/ESA+ cell population and reinforced self-renewal and tumor-initiating ability." (PMID 28388562, 2017). "In addition, measurement of the CD44+CD24− breast CSC population also demonstrated that ectopic expression of ZEB1 led to increased stemness properties in xenografted MDA-MB-231 breast cancer cells." (PMID 28903350, 2017).
breast carcinoma (continued). "This indicated that CD44+Fbs could promote breast cancer cell proliferation and drug resistance by activating Hedgehog pathway via IGF2 secretion." (PMID 28523716, 2017). "Moreover, in breast cancer cases, the EMT state is linked to a cancer stem cell (CSC)-like population harboring the CD44+/CD24− profile, which shows resistance to therapies." (PMID 28240233, 2017). "Then we examined whether altering CD44 isoform expression in breast cancer cells would affect lung metastasis." (PMID 28300837, 2017). "Moreover, immunofluorescence data provide support for our observations that JAK overexpression enhances the expression of CD44 in LDR-exposed breast cancer cells as compared to a control." (PMID 28240233, 2017). "We further investigated whether CD44/CD24 ratio was also correlated with the tumorigenesis of breast cancer cells by comparing the tumorigenicity of the four subtypes of cell lines in the xenotransplanted models." (PMID 29062075, 2017). "Therefore, CD44+Fbs and CD44−Fbs were sorted out to investigate their roles and molecular mechanisms in communication between fibroblasts and breast cancer cells." (PMID 28523716, 2017). "Most importantly, we identified a regulation of the TGFβ pathway-associated proteins TGFβ2, TβR1 and SMAD2, as well as a highly significant upregulation of previously unreported phosphorylation sites of CD44 upon TRAP perturbation in the MDA-MB-231 breast cancer cell line." (PMID 28915803, 2017). "In breast cancer cells, YB-1 promotes the transcription of CD44 and CD49f." (PMID 27911878, 2017). "This suggests that CD44 on fibroblasts protects breast cancer cells from death." (PMID 28523716, 2017). "We found that GFP-positive cells treated with conditioned medium upregulated the expression of CD133 and and the epithelial carcinoma marker found to overexpressed in breast carcinoma Epcam in addition to CD44+/CD24−/low, suggesting that they had differentiated into CSC-like cells." (PMID 28754894, 2017). "Thus far, we have shown that bone-derived OPN influences the migratory ability and stem-like phenotype of breast cancer cells via CD44 and RGD-dependent integrins." (PMID 28498874, 2017). "Therefore, we first determined the effect of CCL2 gene silencing on the numbers of CD24-/CD44+ cells, a well characterized breast cancer stem cell population." (PMID 27283985, 2016). "Our previous findings suggested that CD44 expression may limit endocrine response in breast cancer cells." (PMID 27379207, 2016). "Therefore, the CD44+ is heterogeneous; nevertheless the expression of CD44 is correlated with a more aggressive phenotype in breast cancer and with poor outcome of patients with basal-like breast cancer." (PMID 26673618, 2016). "In this context, we explored whether p63 isoforms could regulate CD44 isoforms expression also in breast cancer." (PMID 27494839, 2016). "To characterize the role of neurotransmitters, neuropeptides, neurotrophic factors, and axonal guidance molecules in breast cancer progression, we analyzed the expression of several neurogenes in breast cancer patients and in CD44 and CD24 expression databases." (PMID 26673618, 2016). "Therefore, we next analyzed the expression of CD44 protein in breast cancer cells stably expressing WNT5A protein." (PMID 27623766, 2016). "Phenotypically, breast cancer stem-like cells (BCSCs) express high CD44 (cell-surface glycoprotein CD44) and low CD24 (cell-surface glycoprotein CD24) (CD44high/CD24low) and also have increased ALDH1 (aldehyde dehydrogenase 1) activity (identified by ALDEFLUORTM assay, StemCell Technologies)." (PMID 26821054, 2016). "In breast cancer, CD44+/CD24_/low cells, posess stem cell–like properties." (PMID 27529753, 2016). "However, high CD44 expression levels also characterize the CSC sub-population in breast cancer, agreed by most researchers as having the CD44+/CD24low/− phenotype." (PMID 27835603, 2016).